HJURP (Holliday junction recognition protein)
Diseases named in the same sentence as HJURP in open-access papers (continued):
Sharing a sentence is not in itself a finding about the gene and the disease.
cancer (continued). "Finally, targeting specific proteins, such as HJURP, which play key roles in cancer progression across multiple types of cancer, could provide new insights and pathways for developing targeted therapies in STAD." (PMID 39478860, 2024). "These properties suggest that HJURP may be a possible target for the treatment of certain cancers." (PMID 37025176, 2023). "This may explain why CENP-A and HJURP are highly expressed in cancer cells." (PMID 34493071, 2021). "Thus these findings support the hypothesis that alterations in HJURP might play an important role in cancer development." (PMID 20211017, 2010). "This study found that in cancer types with over 12 tumor and para-cancer tissues, the genes RRM2, TK1, CCNB1, DLGAP5, CCNA2, MYBL2, and HJURP were repeatedly overexpressed across various cancer tissues." (PMID 39669580, 2024). "Cancer cells become “addicted” and require the sufficient expression of CENP-A and HJURP to ensure centromere identity is maintained and chromosome segregation is achieved/protected in the face of widespread genomic instability." (PMID 32708729, 2020). "Based on these connections, we searched for specific types of human cancers in which CENP-A and HJURP mRNA is up-regulated." (PMID 28356341, 2017). "In order to identify the specific context in which HJURP and CENP-A are transcriptionally up-regulated in human cancers, we first explored data from The Cancer Genome Atlas (TCGA)." (PMID 28356341, 2017). "Therefore, whether or not the HJURP polymorphism rs3771333 also plays a similar role in different types of cancer warrants further investigation." (PMID 26863619, 2016). "Altogether, the list of 14 core genes contains seven genes involved in CENP-A assembly (CENP-A, -N, -M, -K, -L, HJURP and MIS18B), implying an important role for this biological process in cancer progression." (PMID 27577169, 2016). "The role of the histone chaperone HJURP in the deposition of CENP-A at the centromere is well known, and previous studies have demonstrated that knockdown of HJURP in cancer cells strongly affects not only CENP-A deposition but also centrosomes and chromosome stability." (PMID 35955489, 2022). "Although cell-based or animal-based research evidence support the association of Holliday junction recognition protein (HJURP) with cancers, no pan-cancer investigation has been reported." (PMID 35274047, 2022). "Importantly, DAXX is also upregulated in some cancer cell lines where CENP-A is upregulated, and both DAXX and HJURP have structurally similar histone binding domains." (PMID 32708729, 2020). "Thus, cancer cells would adapt to more frequent rounds of replication and mitosis by up-regulating CENP-A and HJURP protein levels to increase the efficiency of centromere propagation, similar to a mechanism of nononcogene addiction." (PMID 28356341, 2017). "The Holliday Junction Recognition Protein (HJURP) is a centromeric protein that was recently shown to be essential for regulating centromeric chromatin assembly during the cell cycle and for chromosomal stability in immortalised cancer cells." (PMID 24039914, 2013). "Misregulation of kinetochore proteins such as HJURP has been observed in various cancers, however the biological relevance of this observation is not well understood." (PMID 21980305, 2011). "Compared to adjacent normal tissues, HJURP expression was significantly upregulated in nearly all types of cancer tissues, regardless of whether the samples were paired or unpaired." (PMID 40290723, 2025). "The ectopic expression of HJURP has been reported in several cancers, but not CCA." (PMID 35965590, 2022).
cancer (continued). "However, the physiological basis for these observations is not well understood, nor is it known if HJURP overexpression plays a direct role in cancer initiation or progression." (PMID 21980305, 2011). "Such correlation is also found in other types of human cancer, such as cancers from lung, ovary, prostate (data not shown), suggesting that compatible mRNA levels of HJURP and CENPA might be required for tumor progression." (PMID 20211017, 2010).
tumor (48 papers, 2010 to 2026). "Previously, HJURP was reported to be associated with tumor-infiltrating immune cells, immune checkpoints, and immune suppression in HCC32,33." (PMID 38561384, 2024). "Firstly, HJURP nuclear immunopositivity was correlated with increased tumor size, and cytoplasmic HJURP overexpression was linked to ciliary body involvement, all factors heralding a grimmer patients’ prognosis when present." (PMID 39200236, 2024). "HJURP nuclear positivity also correlated with advanced T-status (p = 0.054), chromosome 3 loss (p = 0.042) and increased tumor size (p = 0.03)." (PMID 39200236, 2024). "Further research is called for to investigate the potential tumor-promoting role of HJURP in TETs as well as its diagnostic value." (PMID 37958340, 2023). "Extensive research has emphasized the role of DAXX and HJURP, among other biomolecules implicated in epigenetic mechanisms, in the pathogenesis of a great variety of neoplasms." (PMID 37958340, 2023). "HJURP immunoexpression in ovarian cancer cases has been investigated in two studies, both of which underlined its tumor-promoting properties." (PMID 37958340, 2023). "In conclusion, both DAXX and HJURP are implicated in prostate carcinogenesis, with their overexpression appearing to hold value for disease staging and tumor grading as well as patients’ prognosis, in the case of DAXX." (PMID 37958340, 2023). "In the current review, we aim to document the studies investigating the association between DAXX and HJURP expression with human neoplasia of various tissues, as well as the possible correlations with clinicopathological parameters." (PMID 37958340, 2023). "Of note, the expression of DAXX and HJURP has been associated with a multitude of clinicopathological parameters, including disease stage, tumor grade, patients’ overall and disease-free survival, as well as lymphovascular invasion." (PMID 37958340, 2023). "Meanwhile, we found that HJURP knockdown and HJURP mutations were associated with better tumor prognosis." (PMID 36460821, 2022). "Our results showed that the hypomethylation status of HJURP was associated with poor tumor prognosis." (PMID 36460821, 2022). "Further investigations of the mechanisms of HJURP in tumor development and its association with sensitivity to radiotherapy are clearly warranted." (PMID 20211017, 2010). "Additionally, elevated HJURP levels were associated with advanced tumor stages and poorly differentiated tumor samples, suggesting its role in tumor progression." (PMID 39649097, 2024). "Moreover, immunohistochemistry (IHC) of serial sections from HCC patients proved the elevated expression of ASF1A and HJURP in tumor tissues, and HCC patients in the high-risk group had poorer prognosis by IHC staining of HCC tissue microarrays." (PMID 38561384, 2024). "Among them, death domain-associated protein (DAXX) and Holliday junction recognition protein (HJURP) are two of the most extensively studied biomolecules due to their central contribution in a variety of epigenetic modifications implicated in neoplasia." (PMID 37958340, 2023). "Four studies in total underline the tumor-promoting role of HJURP in BC specimens." (PMID 37958340, 2023). "Therefore, it is possible that aberrations in HJURP expression are implicated in kidney carcinogenesis, which include both down- and upregulated expression in tumor tissues." (PMID 37958340, 2023). "DAXX and HJURP are implicated in a multitude of cellular processes, including telomere lengthening, cell apoptosis, chromosome stability, and regulation of various oncogenes’ expression, all of which play key roles both in tumorigenesis and tumor suppression." (PMID 37958340, 2023). "Abnormal activation of HJURP may be linked to unrestricted proliferation of tumor cells, an effect associated with enhanced chromosomal stability and promotion of DNA DSB repair via the homologous recombination pathway." (PMID 37025176, 2023).
tumor (continued). "In conclusion, our study suggests for the first time a possible association between the overexpression of histone variant CENP-A and its dedicated chaperone HJURP in the evolution and progression of TETs, being associated with lymphocyte-rich tumors and advanced tumor stage." (PMID 35955489, 2022). "The role of HJURP in tumor development, and especially in BCa, is still unclear and it remains to be elucidated, as it appears that HJURP could serve as a novel diagnostic and prognostic biomarker for the management of BCa." (PMID 35884419, 2022). "In agreement with these in vitro findings, xenografts injected with Capan-2 cells bearing HJURP inserts displayed exceeding tumor formation compared to control models, whereas deficiency of HJURP in the SW 1990 cells significantly inhibited the tumor growth in vivo." (PMID 32439850, 2020). "HJURP may participate in the immunogenicity mechanisms of different tumor types, and its immune and mutation characteristics may be the potential biomarker for tumor stage diagnosis and prognosis." (PMID 36460821, 2022). "Each of the four genes (HJURP, CDK1, FOXM1, and CHEK1) identified in the model has been implicated in cell cycle regulation and tumor development." (PMID 40299539, 2025). "Prior studies have demonstrated that HJURP promotes tumor cell proliferation and chemoradiotherapy resistance by participating in cell cycle regulation and maintaining genomic stability." (PMID 40290723, 2025). "HJURP, which is essential for maintaining centromeric chromatin, enhances tumor cell proliferation and is correlated with aggressive tumor characteristics and unfavorable clinical outcomes in LIHC." (PMID 40251374, 2025). "To evaluate the expression profile of HJURP in tissues, we analyzed the protein levels of HJURP in paired cancerous and adjacent non-tumor tissues from 6 GC patients." (PMID 40290723, 2025). "HJURP and CENPA mRNA overexpression exhibited strong association with tumor epithelioid histology and was linked to worse prognosis." (PMID 39200236, 2024). "Our present study attempts to shed light on the implication of DAXX, HJURP and CENPA in the carcinogenesis of UMs and associate their immunohistochemical expression in tumor tissues with patients’ clinicopathological parameters and prognosis." (PMID 39200236, 2024). "In the spatial transcriptomic analysis, we observed that HJURP is predominantly expressed in tumor cells, with minimal expression in immune cells, including macrophages." (PMID 39649097, 2024). "In the TCGA cohort, HJURP expression was significantly elevated in tumors, as compared between paired tumor and adjacent normal samples (p < 0.001)." (PMID 39649097, 2024). "Intriguingly, the RNA levels of ASF1A and HJURP also gradually increased with tumor stage progression in the TCGA-LIHC data." (PMID 38561384, 2024). "In the TCGA-LUAD cohort, age over 70 years (p < 0.01), tumor stage (all other stages vs Stage I: p < 0.001), and HJURP expression (p < 0.001) were independent prognostic factors." (PMID 39649097, 2024). "Analysis conducted above indicated that HJURP expression in BCa tissues increases with tumor malignancy." (PMID 39139392, 2024). "Statistical analysis showed increasing mean densities of ASF1A and HJURP with tumor development and progression." (PMID 38561384, 2024).
tumor (continued). "In the GSE31210 cohort, age (p = 0.014), tumor stage (Stage II vs Stage I: p < 0.001), and HJURP expression (p = 0.042) were independent prognostic factors." (PMID 39649097, 2024). "Using spatial transcriptomics data, we observed that in LUAD tumor tissues, the regions of HJURP expression correspond to tumor areas rather than regions populated by immune cells." (PMID 39649097, 2024). "In further studies, we calculated the activation levels of 14 tumor development-related signaling pathways and evaluated their correlation with HJURP expression." (PMID 39649097, 2024). "HJURP expression increased with advanced tumor stage (TCGA-LUAD: p < 0.001, GSE31210: p < 0.001, GSE68654: p = 0.012, GSE72094: p = 0.012)." (PMID 39649097, 2024). "The immunohistochemical assay showed that the level of HJURP protein was significantly higher in tumor tissues than in normal mammary gland tissues." (PMID 39139392, 2024). "Our previous study demonstrated that HJURP, an oncogene upregulated in PCa cells, plays a role in tumor proliferation." (PMID 39405980, 2024). "Of all the H3–H4 histone chaperones, HJURP is significantly highly expressed in almost all tumor types." (PMID 38561384, 2024). "Immunohistochemical (IHC) staining showed that ASF1A and HJURP were expressed more highly in tumor tissues than in normal tissues." (PMID 38561384, 2024). "In turn, overexpression and knockdown experiments in PDAC cell lines, as well as analysis of mouse xenograft models, showed that HJURP promoted viability, tumorsphere formation, and migration and invasion in vitro, and tumor growth and metastasis in vivo." (PMID 37025176, 2023). "Some researchers found that HJURP is a potential independent prognostic marker of ccRCC and can play an important role in the tumor microenvironment by regulating immune cell infiltration." (PMID 36941564, 2023). "Several studies have reported that HJURP acted as an oncogene affecting chromosome segregation and controlling accelerated division of tumor cells." (PMID 37025176, 2023). "To summarize, an increasing amount of research in numerous types of neoplasia has underlined the implications of DAXX and HJURP in disease pathogenesis and has highlighted clinicopathological and prognostic correlations." (PMID 37958340, 2023). "In the present review, we present data reported from studies investigating DAXX and HJURP expression, either on mRNA or protein level, in human tissue samples from various types of neoplasia." (PMID 37958340, 2023). "On the other hand, HJURP negatively impacts neoplastic disease of this specific organ, potentially aiding in disease precise diagnosis and prognosis." (PMID 37958340, 2023). "There was also a significant correlation between upregulated HJURP expression and clinical features such as tumor lesion >5 cm, tumor stage (AJCC), BCLC stage, and microvascular invasion." (PMID 37025176, 2023). "Although more detailed studies on the mechanisms by which HJURP promotes HCC and CCA, as well as its impact on tumor immunogenicity, are warranted, these findings suggest that HJURP is a potential biomarker and therapeutic target for HCC and CCA." (PMID 37025176, 2023). "On the contrary, HJURP acts as a tumor-promoter in this specific organ, with possible implications in disease diagnosis and prognosis." (PMID 37958340, 2023). "HJURP is also overexpressed and plays a tumor-promoting role in gastric carcinoma (GC) and colorectal cancer (CRC)." (PMID 37025176, 2023). "As a result, HJURP can participate in various cell proliferation-related pathways and promote the proliferation of tumor cells." (PMID 35783358, 2022).